IFIT3 (interferon induced protein with tetratricopeptide repeats 3)
Diseases named in the same sentence as IFIT3 in open-access papers (continued):
Sharing a sentence is not in itself a finding about the gene and the disease.
cancer (continued). "Notably, HLA-I– cancer cells acquiring a mesenchymal status were associated with enhanced mRNA levels of the IFN-stimulated genes IFIT1, IFIT2, IFIT3, IFI6, IFI27, and CCL2." (PMID 35503263, 2022). "In addition, there were multiple genes induced that are involved with cell and organelle structure and function (PNCK, UBD, CDH2, HERC5) and importantly, genes associated with the prostate, AR (MMP7, CDH2, ENO2, IGFBP3) and cancer (IFIT3, IFI44L)." (PMID 29416764, 2018). "BC5 cancer cells and normal BN1 cells demonstrated lower transcriptional activation that was inversely associated with the baseline expression level of the gene namely the snoRNA analogue induced a 10- and 32-fold increase in IFIT3 mRNA, respectively." (PMID 29986702, 2018). "Interestingly, a more profound desmoplastic reaction was seen in tumors derived from cancer cells with higher levels of IFIT3 expression." (PMID 25650658, 2015). "We sought to identify whether ETV7-mediated cancer progression is based on the expression of IFIT3." (PMID 38200280, 2024). "However, IFIT3 expression has been shown to be detrimental for patient outcomes in other cancers." (PMID 34622927, 2021). "Meanwhile, PD-L1 knockdown or over-expressed reversed cancer cell stemness, migration, invasion, and PI3K/AKT signaling pathway which were regulated by IFIT3." (PMID 38273364, 2024). "Elevated levels of IFIT1, IFIT3 and IFIT5 have been shown to play significant roles in cancer progression, while the decreased expression of IFIT2 has been reported to enhance invasion, tumor progression, and drug resistance in various cancer types." (PMID 36979874, 2023). "Although more work is required to accurately elucidate the impact of IFIT proteins in cancer, recent investigations reveal that IFIT1, IFIT3, and IFIT5 promote metastasis, while IFIT2 acts against neoplastic cells by promoting apoptosis." (PMID 36851555, 2023). "We then analyzed the expression of two well-known interferon-induced genes, IFIT3 and IFI44, using mRNA expression data from the Cancer Cell Line Encyclopedia." (PMID 36882786, 2023). "Among 33 types of human cancers, IFIT1, IFIT2, IFIT3, IFIT5 were abnormally expressed in 21, 23, 24 and 23 cancer types respectively." (PMID 37980495, 2023). "Consistent with the findings in human cancer cell lines, the canonical IFN signaling genes such as Isg15, Ifi44, Ifit3, and Ddx58 were induced at a significantly higher magnitude in Rad21-knockdown cells upon IFN-β stimulation." (PMID 36201246, 2022). "In particular, the expression levels of genes, such as IFI6, MX1, IFIT1, IFIT3, ISG15, OAS1, and OAS2, which belong to the cancer-promoting ISG subset IRDS, were markedly increased." (PMID 35618021, 2022). "From a functional point of view, genes involved in interferon signaling and cytotoxicity (IFIT1, IFIT3, and MX1) are upregulated in COVID/cancer cohort." (PMID 34716309, 2021). "IFIT3 mRNA was increased 30- and 20-fold following treatment with the immune-stimulating RNA (isRNA) in MDA-MB-231 cancer cells and MCF10A normal cells, respectively." (PMID 29986702, 2018). "Three out of the six most significant canonical pathways were related to the cancer suppression or prevention, namely Interferon Signaling (IRF9, IFIT3), BER pathway (XRCC1) and DNA Double-Strand Break Repair by Non-Homologous End Joining (XRCC1)." (PMID 27421136, 2016). "IFIT3 specifically targets programmed death ligand 1 (PD-L1) expression by activating the PI3K/AKT signaling pathway, thereby regulating the epithelial-mesenchymal transition (EMT) and cancer stem cell (CSC) activity." (PMID 40061935, 2025). "Our results reveal that IFIT3 promotes EMT and cancer stemness by targeting PD-L1 to activate PI3K/AKT signaling pathway in HNSC, and targeting IFIT3 may be a novel strategy for the treatment of patients with HNSC." (PMID 38273364, 2024).
cancer (continued). "Interferon-induced protein with tetratricopeptide repeats 3 (IFIT3) was one of the four known IFIT family members in humans, which is an important component of the antiviral immune response and played significant roles in cancers." (PMID 38200280, 2024). "Indeed, the expression of CCL8, IFIT1, IFIT3, IFI27, MX1, and RSAD2 has previously been considered favorably prognostic in several types of cancer." (PMID 36180872, 2022). "Because we did not observe any correlation of IFIT3 expression and the ER/PGR/HER2 status of cancer cells, we suggest that IFIT3 expression be tested regardless of ER/PGR/HER2 status if innate immunity activators will be used." (PMID 29986702, 2018). "Moreover, in HNSCC, IFIT3 regulates EMT and cancer stem cells by targeting PD-L1 through the PI3K/AKT pathway and may participate in responses of HNSCC cells to EGFR/ERBB inhibition." (PMID 40564154, 2025). "Therefore, IFIT3 may serve as an oncogene and participate in HNSC carcinogenesis and progression, consistent with a previous study in other cancer." (PMID 38273364, 2024). "In addition, IFIT1 and IFIT3 are critical for EGFR recycling and activation in other cancers." (PMID 35280763, 2022). "IFNα exposure led to 3.5-fold increase in IFIT3 mRNA in BN1 normal cells and no significant change in BC5 cancer cells." (PMID 29986702, 2018).
bacterial infection (3 papers, 2020 to 2025). "Data showed that females exhibit higher levels of anti-viral type 1 interferons IFNA17, IFNA2, IFIT1, IFIT3 and IFNE in the immune tissues/cells, which serve as the first line of defense against viral and bacterial infections." (PMID 33271804, 2020). "To assess whether glial cell production of IFN-β during bacterial infection promotes ISG protein production, we measured the levels of two canonical ISGs, including IFN-induced proteins with tetratricopeptide repeats 1 (IFIT-1) and IFIT-3." (PMID 41341589, 2025).
cardiovascular disease (2 papers, 2021). "Previous studies have demonstrated that IFIT1, IFIT3 and IFIT5 play an important regulatory role in cardiovascular disease." (PMID 34753383, 2021). "The top different expressed genes in the cardiovascular disease or MI were identified as IFIT2 and IFIT3." (PMID 34884921, 2021). "Furthermore, three potential signature genes (IFIT2, IFIT3 and IFI44L) were identified in cardiovascular disease knowledge portal." (PMID 34884921, 2021).
infectious disease (2 papers, 2018). A disorder directly resulting from the presence and activity of a microbial, viral, or parasitic agent in humans. "Many genes in the KLHDC7B-downregulated dataset are related, such as STAT1, IFIT3, and MX1, with the antimicrobial or infectious disease properties showing decreased expression." (PMID 30150751, 2018).
heart disease (1 paper, 2021). "It is significant evidence that that three signature genes (IFIT2, IFIT3 and IFI44L) are linked to heart disease and used as potential biomarker for ISCM." (PMID 34884921, 2021).
IFIT3 also shares sentences with these, for which no sentence is quoted: ovarian carcinoma (3 papers); sarcoidosis (3); tuberculosis (3); AIDS (2); Alzheimer disease (2); epilepsy (2); glioblastoma (2); H1N1 virus infection (2); hepatitis C (2); inflammatory myopathies (2); primary Sjögren syndrome (2); viral diseases (2); vitiligo (2); amyotrophic lateral sclerosis (1); Arthritis (1); asthma (1); astrocytoma (1); colorectal tumors (1); dementia (1); diabetes (1); epileptic seizures (1); germinoma (1); heart failure (1); hematological malignancies (1); Hepatitis (1); Hyperbilirubinemia (1); hyperlipidemia (1); liver fibrosis (1); lung squamous cell carcinoma (1); measles (1).
A further 22 diseases each share a sentence with IFIT3 in 1 paper.